COPS3 (COP9 signalosome subunit 3)
Description:
Component of the COP9 signalosome complex (CSN), a complex involved in various cellular and developmental processes. The CSN complex is an essential regulator of the ubiquitin (Ubl) conjugation pathway by mediating the deneddylation of the cullin subunits of SCF-type E3 ligase complexes, leading to decrease the Ubl ligase activity of SCF-type complexes such as SCF, CSA or DDB2. Mediates the interaction between the desmosome and COP9 signalosome complex (CSN) protein complex. As a result of this interaction, promotes keratinocyte differentiation via deneddylation of EGFR resulting in a reduction in EGFR protein stabilization and translocation away from the cell membrane.
Synonyms: SGN3; CSN3
Tractability: PROTAC: ubiquitination databases record sites on it; its protein half-life has been measured.
Gene: Protein-coding gene on chromosome 17 (17,246,616 to 17,281,303, reverse strand). Ensembl gene ENSG00000141030.
Subcellular location: Cytoplasm; Nucleus; Cell junction
Subcellular location (Human Protein Atlas): Cytosol; Nucleoplasm
Pathways (Reactome):
DNA Repair: DNA Damage Recognition in GG-NER; Formation of TC-NER Pre-Incision Complex
Metabolism of proteins: Neddylation
Vesicle-mediated transport: Cargo recognition for clathrin-mediated endocytosis
Gene Ontology:
Molecular function: protein binding
Biological process: positive regulation of keratinocyte differentiation; protein deneddylation; protein neddylation; regulation of protein neddylation; response to light stimulus; signal transduction; ubiquitin-dependent protein catabolic process
Cellular component: cell-cell junction; COP9 signalosome; cytoplasm; cytosol; nucleoplasm; nucleus; perinuclear region of cytoplasm; anchoring junction
Genetic constraint (gnomAD): Loss-of-function variants: 10 observed, 48.79 expected, observed/expected ratio (o/e) 0.2, 90% interval 0.12 to 0.35. The upper end of that interval is the gene's LOEUF score, 0.35, which puts it in group 1 of 6, group 1 being the genes least tolerant of losing a copy. Missense variants: 288 observed, 459.21 expected, observed/expected ratio (o/e) 0.63, 90% interval 0.57 to 0.69. Synonymous variants: 168 observed, 170.95 expected, observed/expected ratio (o/e) 0.98, 90% interval 0.87 to 1.12.
Homologues: Orthologues: chimpanzee COPS3 (100% identical), macaque COPS3 (100% identical), dog COPS3 (99% identical), guinea pig COPS3 (99% identical), rat Cops3 (99% identical), mouse Cops3 (99% identical), rabbit COPS3 (99% identical), tropical clawed frog cops3 (95% identical), pig COPS3 (85% identical), zebrafish cops3 (81% identical), Drosophila melanogaster CSN3 (54% identical), Caenorhabditis elegans rpn-3 (17% identical). Paralogues in human: PSMD3 (24% identical).